RN7SL818P (RNA, 7SL, cytoplasmic 818, pseudogene)
Gene: Miscellaneous RNA gene on chromosome Y (24,210,958 to 24,211,216, reverse strand). Ensembl gene ENSG00000274234.
Homologues: Orthologues: chimpanzee Metazoa_SRP (54% identical). Paralogues in human: RN7SL725P (100% identical), RN7SL536P (77% identical), Metazoa_SRP (77% identical), RN7SL106P (77% identical), RN7SL238P (77% identical), RN7SL545P (77% identical), RN7SL759P (77% identical), RN7SL417P (75% identical), RN7SL209P (71% identical), RN7SL736P (69% identical), RN7SL214P (68% identical), RN7SL176P (67% identical), and 705 more.